GDF15 (growth differentiation factor 15)
Diseases named in the same sentence as GDF15 in open-access papers (continued):
Sharing a sentence is not in itself a finding about the gene and the disease.
Obesity (continued). "We confirmed previous findings, suggesting that smoking, obesity, hs-CRP, etc. are strongly correlated with GDF-15 levels, and these are factors that also have been associated with CKD." (PMID 34706669, 2021). "The longitudinal associations of the anti-inflammatory GDF-15 with IgA, IgG and the IgA*IgG product in children with higher BMI or higher renal fat accumulation suggest a role of GDF-15 in human obesity through the regulation of the immune adaptive system." (PMID 34521901, 2021). "These mice were resistant against diet-induced obesity and insulin resistance, due to an increase in lipolysis in adipocytes and hepatocytes, which was shown to be GDF15-mediated." (PMID 34831213, 2021). "According to compelling evidence, GDF15 functions as an anti-obesity hormone by decreasing food intake." (PMID 34877504, 2021). "Activation of the ISR in adipose tissue improved diet-induced obesity and diabetes by inducing the secretion of the adipokine growth differentiation factor 15 (GDF15) to decrease the specific intake of a high-fat diet (HFD)." (PMID 34877504, 2021). "Firstly, transgenic mice overexpressing GDF15 from birth were protected from diet-induced obesity, hepatic steatosis, and glucose intolerance." (PMID 33903632, 2021). "Because of its action as an appetite suppressant, GDF15 is being explored as a potential therapy for obesity." (PMID 34187898, 2021). "It is worth noting that nausea and emesis are legitimate concerns for a GDF15-based obesity therapeutic." (PMID 33903632, 2021). "Extensive literature describes GDF15 as a biomarker for a number of diverse pathologies or conditions such as diabetes, cardiovascular disease, obesity, cancer, mitochondrial disease, and aging." (PMID 33464381, 2021). "Secondly, GDF15 administration through either viral vectors or recombinant protein injection in a genetic obesity ob/ob mouse model reduced food intake, body weight, and improved overall metabolic parameters such as glucose tolerance and insulin sensitivity." (PMID 33903632, 2021). "In a mouse model of adipocyte specific defect in oxidative phosphorylation (OXPHOS) both FGF21 and GDF15 were found to be induced and both were shown to be instrumental in protection from obesity and insulin resistance induced by high fat diet feeding." (PMID 33464381, 2021). "For example, while activation of the GDF15–GFRAL pathway can lead to cancer-associated anorexia-cachexia syndrome, it can also ameliorate obesity-associated morbidities." (PMID 34831213, 2021). "Growth differentiation factor-15 (GDF15) was previously reported to be associated with inflammation, and many biological processes and diseases, including cancer and obesity." (PMID 34335566, 2021). "Growth differentiation factor 15 (GDF15), which belongs to the transforming growth factor (TGFB) superfamily, is strongly associated with several diseases such as obesity, cancer and cardiovascular diseases as well as with aging." (PMID 34948405, 2021). "A variety of analogues and mimetics for FGF21 and GDF15 have been investigated for treatment of obesity." (PMID 34777390, 2021). "On the other hand, enhancement of GDF15 expression is a promising therapeutic strategy in the treatment of obesity." (PMID 32427329, 2020). "The prevalence of cardiovascular risk factors in our group of renal transplanted children is high, and we found significant univariate associations between GDF-15, hyperuricemia, elevated triglycerides, low HDL, and obesity." (PMID 32089755, 2020). "It should be noted that in contrast to our work, the authors of this study found that the glucoregulatory actions of chronic metformin treatment in diet-induced obesity were dependent on the presence of GDF15." (PMID 32310257, 2020). "Despite these findings demonstrating a role of macrophage-produced GDF-15 in obesity and T2D, little is known about the stimulus and the molecular mechanism driving GDF15 expression in macrophages in metabolic diseases." (PMID 33302552, 2020).
Obesity (continued). "Growth differentiation factor 15 (GDF15) belongs to the transforming growth factor β superfamily and is dysregulated in metabolic disease including obesity and diabetes mellitus." (PMID 33003626, 2020). "Here we examined the novel circulating biomarker GDF15 in cardiac surgery patients with heart disease given the suggested pre-clinical role of GDF15 in obesity." (PMID 32671100, 2020). "This review focuses mainly on the role of GFLs in neurodegeneration; extensive data on GDF15 functions in obesity and NRTN in diabetes are provided elsewhere." (PMID 32911810, 2020). "GDF15 is suggested to be a reliable predictor of disease progression in certain tumors, inflammatory diseases, cardiovascular disease, and obesity." (PMID 32265845, 2020). "While we found significant univariate associations between GDF-15 and risk factors for CVD as elevated triglycerides, low HDL and obesity, mGFR, and hemoglobin were the only significant predictors of GDF-15 in an adjusted analysis." (PMID 32089755, 2020). "Pioneering work by Breit’s group established that GDF15 was a potent anorectic factor in the context of cancer and identified its ability to prevent diet-induced obesity in mice long before the discovery of GFRAL." (PMID 32310257, 2020). "Circulating levels of GDF15 are raised in a variety of disease states, including cancer, atherosclerotic cardiovascular disease, and obesity." (PMID 32310257, 2020). "FGF21 or GDF15 increased skeletal muscle expression play protective roles against diet-induced obesity and insulin resistance." (PMID 33374852, 2020). "We were able to demonstrate a significant correlation between GDF15 expression and NT-proBNP, supporting a mechanistic link between cardiac remodeling, obesity and thus potentially HFpEF." (PMID 32671100, 2020). "Univariate associations between GDF-15 and hyperuricemia (p < 0.001), elevated triglycerides (p = 0.028), low HDL (p = 0.038), and obesity (p = 0.028) were found." (PMID 32089755, 2020). "In the present study, we sought to characterize the clinical characteristics and outcomes of patients undergoing elective heart surgery in which blood and tissue samples were assessed for biomarkers, including GDF15 in relation to obesity outcomes." (PMID 32671100, 2020). "To date, GDF15 is shown to have mediated aversive dietary response, influenced the governance of systemic energy balance, and prevented obesity through enhanced thermogenesis and oxidative metabolism." (PMID 32804947, 2020). "In a post hoc analysis of a randomized controlled trial of metformin in patients with obesity and proven coronary artery disease, metformin administration led to substantial and sustained elevations in circulating levels of GDF15." (PMID 32310257, 2020). "The fact that metformin exerts its regulatory effect on weight via GDF15-GFRAL-RET provides proof of principle for GFRAL agonism as a therapeutic strategy in obesity." (PMID 32310257, 2020). "Unsurprisingly, elevated circulating GDF15 levels have been shown to be involved in anorexia nervosa, cancer cachexia, and obesity." (PMID 32928255, 2020). "Transgenic mice overexpressing Gdf15 or mice injected with recombinant GDF-15 are protected against obesity and insulin resistance (IR)." (PMID 33302552, 2020). "The role of GDF-15 in weight regulation is further supported by the observation that GDF-15 transgenic mice are protected against obesity." (PMID 32508832, 2020). "In mice, glial-derived neurotrophic factor receptor alpha-like (GFRAL) is highly expressed in the area postrema and can bind with GDF-15 directly to treat metabolic related diseases such as obesity, diabetes and anorexia/cachexia." (PMID 33201838, 2020). "Representative tissue samples from each obesity group were analyzed for GDF15 by western blot and immunohistochemistry." (PMID 32671100, 2020).
Obesity (continued). "GDF-15 expression can be induced by inflammation, injury, cardiovascular diseases, obesity and malignancy." (PMID 33201838, 2020). "In keeping with these findings, GDF15 is clearly elevated in human and rodent obesity, which is a consequence of sustained overnutrition." (PMID 32310257, 2020). "In fact, several similar lines of dose-dependent mechanism were reported on obesity research; for example, Growth differentiation factor 15 (GDF15) is widely accepted as a secreted protein that reduces food intake in mice." (PMID 32218572, 2020). "Our study is supported by others, suggesting that higher GDF15 expression predicted worse outcomes in heart surgery patients, but its relationship to obesity merited further investigation." (PMID 32671100, 2020). "Notably, genetic ablation of GDF15 in a mouse model of skeletal muscle‐specific deficiency of Crif1, an integral protein of the large mitoribosomal subunit, prevented a mitochondrial stress‐driven improved insulin sensitivity and resistance to diet‐induced obesity." (PMID 32026535, 2020). "In other settings like obesity, induction of GDF15 has been considered a physiological signal of reduced nutritional need and cellular inability to metabolize macronutrients and as such to aid in restoring homeostasis." (PMID 32928255, 2020). "Despite macrophages have been recently suggested as a key source of GDF-15 in obesity, little is known about the regulation of GDF-15 in these cells." (PMID 33302552, 2020). "In consideration of the enormous potential of GFRAL modulators to counteract overeating and obesity, the GDF-15/GFRAL/RET pathway is the most active area for drug development in this endeavor." (PMID 32508832, 2020). "Results from previous studies have shown that individuals with obesity or diabetes have significantly higher GDF-15 concentrations than control participants." (PMID 30350239, 2019). "Because of these protective effects, GDF-15 has been considered to be beneficial for the prevention and treatment of obesity and hyperglycaemia." (PMID 30350239, 2019). "When put on obesogenic high fat diet, male GDF15 knockout mice quickly gained more weight than wildtype mice and developed worsened glucose tolerance, suggesting a protective role of endogenous GDF15 in response to obesity-inducing conditions." (PMID 30070999, 2018). "Although GDF15 emerges as a critical driver of metabolism in diet-induced obesity, the impact of body weight on hepatic GDF15 expression remains unexplored." (PMID 30533221, 2018). "To investigate the role of endogenous GDF15 in obesity development, we put GDF15 knockout mice and wildtype controls on high fat diet for the mice to develop diet-induced obesity." (PMID 30070999, 2018). "To investigate if the circulating endogenous GDF15 plays a functional role in obesity development, we put GDF15 knockout mice and wildtype controls on high fat diet and studied the impact of GDF15 deficiency in these diet-induced obese (DIO) mice." (PMID 30070999, 2018). "Based on these data, GDF15/GFRAL signalling emerges as a promising target to treat obesity in the future." (PMID 30533221, 2018). "First, one of the key roles of thyroid hormone is to up-regulate UCP1 expression in BAT to increase adaptive thermogenesis and counteract obesity, which overlaps with the action of GDF15." (PMID 30687235, 2018). "Given that GFRAL is expressed solely in hindbrain neurons but not in peripheral tissues in mice, these results suggest that exogenous GDF15 administration leads to resistance to diet-induced obesity via GFRAL-dependent anorexic action in brain." (PMID 29717162, 2018). "GDF15 administration or GDF15 overexpression has been reported to have anti-obesity and anti-diabetic effects." (PMID 29717162, 2018). "Compared to the wildtype control animals, GDF15 knockout mice had higher food intake and lower metabolic rate, both likely have contributed to the aggravated obesity development." (PMID 30070999, 2018).
Obesity (continued). "Increased serum concentrations of GDF15 have been reported in patients with anorexia nervosa and obesity, inspiring us to explore the function of GDF15 on the adipocytes." (PMID 29566722, 2018). "In another study, GDF15 transgenic mice were resistant to diet- and genetically induced obesity and exhibited improved insulin sensitivity due to a reduction in NLRP3 inflammasome activity in adipose tissue, in the context of obesity and insulin resistance." (PMID 29674655, 2018). "This is because FGF-21 and GDF-15 have also been found elevated in other conditions, such as diabetes, hepatopathy, renal insufficiency, malignancy, or obesity." (PMID 29385732, 2018). "GDF-15 has been studied before in the context of cancer, obesity, type II diabetes, malaria and heart disease." (PMID 26867126, 2016). "Several investigations evidenced a relation between GDF-15 and markers of metabolic dysfunction e.g. impaired fasting glucose, insulin resistance and glucose metabolism, obesity, inflammation and finally aging." (PMID 27056183, 2016). "In a study concerning obesity and GDF-15 level, it was found that GDF-15 levels were higher in obese group than in nonobese group." (PMID 26075263, 2015). "More research needs to be carried out to find if administration of GDF-15 has any role to reduce inflammation or early pathological changes in diabetes and obesity." (PMID 26273671, 2015). "In patients with obesity, expression of GDF15 can be induced by very low calorie diet (VLCD), which seems counter to the findings of the present study." (PMID 23799024, 2013). "This review also discusses the multiple sources of GDF15 in obesity and in response to its surgical treatment, where pathological, pharmacological, and behavioral factors may all be important contributors." (PMID 41915091, 2026). "Additional prospective studies are required to validate the clinical use of GDF-15 in quantifying the relationship between obesity, heart failure, and subclinical atherosclerosis, as well as to assess its significance in individualized risk estimation and disease prevention." (PMID 41597417, 2026). "Thus, GDF-15 can be considered a biomarker capable of quantifying the interaction between obesity, atherosclerosis, and HF." (PMID 41597417, 2026). "Since there are several mechanisms that could link obesity, heart failure, and atherosclerosis through GDF-15, an important question remains: should GDF-15 be interpreted as a risk biomarker or an active mediator in this triad?" (PMID 41597417, 2026). "Future research should aim to clarify whether GDF-15 serves as a biomarker that quantifies cardiometabolic stress across obesity and HF, and whether it can enhance early detection of subclinical atherosclerosis." (PMID 41597417, 2026). "The relationship between GDF-15 and HF, especially HFpEF in the context of obesity, requires focused investigation, as metabolic inflammation and myocardial strain may independently influence GDF-15 expression." (PMID 41597417, 2026). "In addition to their independent effects regulating metabolism, in the present study, we uncovered that FGF21 and GDF15 act synergistically to improve glucose homeostasis and promote resistance to diet‐induced obesity." (PMID 40897647, 2025). "Adult and mouse studies of starvation and obesity show elevated GDF15 at both very high and very low weights, hypothesized secondary to inflammatory changes and stress signalling." (PMID 40019842, 2025). "Circulating GDF15 levels are elevated in individuals with obesity and are even higher in those with obesity and T2D, which may reflect a compensatory anti-inflammatory mechanism during early stages of metabolic disease." (PMID 40530451, 2025). "Notably, CPT-induced GDF15 elevations were obesity dependent, suggesting that the relatively low levels of GDF15 in lean mice were insufficient to suppress food intake and body weight." (PMID 40837873, 2025).
Obesity (continued). "Furthermore, the anti-obesity benefits of artesunate were shown to require GDF15 signaling, as gene deletion of GFRAL or cell-type-specific silencing of GDF15 abolished its metabolic effects." (PMID 40837873, 2025). "Therefore, the objective of this study was to assess circulating GDF15 levels in a cohort of patients with obesity and a cohort of healthy, normal-weight individuals." (PMID 40530451, 2025). "All these data suggest that the duration of obesity and the liver health of the patients may influence circulating GDF15 levels." (PMID 40530451, 2025). "Gdf15 and Fgf21 expression are regulated by similar underpinning molecular mechanisms, and circulating levels frequently increase in tandem during the development of obesity." (PMID 40787810, 2025). "This review synthesizes evidence linking GDF15 to obesity, diabetes, cardiovascular diseases, metabolic liver disorders, cachexia, sarcopenia, and aging while exploring its interactions with key metabolic factors including FGF21, GLP-1, leptin, and glucocorticoids." (PMID 40837873, 2025). "Non-alcoholic fatty liver disease (NAFLD), which reflects the degree of obesity and the risk for T2DM, is associated with increased expression and release of GDF-15, making it a potential biomarker for NAFLD and disease progression, particularly for worsening fibrosis and steatosis." (PMID 40722664, 2025). "Additionally, it would be of interest to explore in future studies variations in the levels of FGF21 and GDF15, considering obesity and severe obesity as separate disease entities, as it has been shown that their pathophysiology can differ significantly." (PMID 40377893, 2025). "In addition, GLCE deficiency in the liver promotes obesity, and reduced GLCE expression further reduces hepatic secretion of GDF15, which in turn interferes with lipid metabolism and energy homeostasis." (PMID 41497483, 2025). "This study demonstrates that a 16-week combined aerobic and resistance training program can significantly improve body composition and modulate the expression of key myokines—GDF-15, apelin-12, and IL-15—in older women, with differential responses observed based on obesity status." (PMID 40725674, 2025). "Depending on the source of origin, GDF15 may exert different metabolic functions, potentially explaining discrepancies among studies examining the impact of obesity and BS on circulating GDF15 levels." (PMID 40530451, 2025). "Notably, among prevalent dietary strategies for obesity management—such as the Mediterranean diet, low-fat diet, high-protein diet, and low-glycemic-index diet—the ketogenic diet uniquely stimulates GDF15 expression." (PMID 40837873, 2025). "Secondly, the increase in GDF15 levels caused by the stress of RYGB surgery could be maintained over time due to a state of GDF15 resistance or reduced sensitivity in people living with obesity." (PMID 40377893, 2025). "Immune cells such as granulocytes and monocytes, which express GDF15 and are activated during inflammation, may contribute, particularly in the liver where immune cell infiltration occurs in obesity." (PMID 40837873, 2025). "Elevated circulating GDF15 levels may also confer some protection against fat accumulation in individuals with obesity." (PMID 40530451, 2025). "By modulating the metabolic activity of lipolytic genes, GDF15 is hypothesized to have diagnostic and therapeutic value in the treatment of IR, T2DM, obesity, and glycolipid metabolism." (PMID 41497484, 2025). "Notably, individuals with obesity or T2DM exhibit significantly higher GDF-15 levels compared to healthy controls." (PMID 41019919, 2025). "Notably, the anti-obesity effects of metformin, a first-line antidiabetic drug, have been shown to be mediated through GDF15." (PMID 41204286, 2025). "GDF15 has been established as a marker of cancer metastasis in pancreatic cancer, and its regulation has also been investigated as a possible treatment for obesity and diabetes." (PMID 40278353, 2025).